PTK6 (protein tyrosine kinase 6)
Diseases named in the same sentence as PTK6 in open-access papers (continued):
Sharing a sentence is not in itself a finding about the gene and the disease.
prostate carcinoma (continued). "Altered intracellular localization of PTK6 in prostate cancer cells, including the PC3 cell line, raised the possibility that the PTK6 gene might harbor mutations that contribute to altered PTK6 localization." (PMID 21479203, 2011). "Recently we showed that cytoplasmic PTK6 promotes growth of prostate cancer cells." (PMID 21479203, 2011). "Also, it was reported that PTEN inhibits PTK6 oncogenic signaling in prostate cancer." (PMID 37273453, 2023). "Earlier we reported that conditional disruption of Pten in the mouse prostate led to activating phosphorylation of membrane-associated PTK614 supporting our hypothesis that PTEN may directly negatively regulate PTK6 activity and/or membrane localization in human prostate cancer cells." (PMID 29142193, 2017). "Furthermore, downregulation of PTK6 enhances anoikis of breast, ovarian and prostate cancer cells." (PMID 26084280, 2015). "We examined PTK6 and SRC in three prostate cancer cell lines (LNCaP, C4-2B, and PC3) and in breast (T47D) and lung (PC-9) cancer cell lines." (PMID 36228719, 2022). "PTEN suppresses oncogenic signaling for prostate cancer through dephosphorylation of PTK6 tyrosine 342(PY342), and PTK6 facilitates cell migration and proliferation by phosphorylating Esp8." (PMID 33109128, 2020). "Cumulatively, these data indicate that PTK6 and PTEN are coregulated at multiple levels in prostate cancer." (PMID 29142193, 2017). "These coimmunoprecipitation experiments demonstrate that endogenous PTK6 and PTEN form a complex in prostate cancer cells." (PMID 29142193, 2017). "Interestingly, inhibition of PTK6 has been proposed for treatment in triple negative breast cancer and PTEN-null prostate cancer." (PMID 34115745, 2021). "Interestingly, by examining PTK6 and PTEN gene expression in the Grasso49 and TCGA48 prostate cancer datasets, we also found PTK6 mRNA expression is often inversely correlated with PTEN gene expression." (PMID 29142193, 2017). "Reintroduction of PTEN into prostate cancer cells lacking functional PTEN leads to PTK6 dephosphorylation and inhibition of its activity and downstream oncogenic signaling." (PMID 29142193, 2017). "As PTEN negatively regulated PTK6 phosphorylation at tyrosine residue 342, we examined whether endogenous PTK6 and PTEN form a complex within DU145 prostate cancer cells." (PMID 29142193, 2017). "The prostate cancer cell line DU145 expresses functional PTEN and PTK6." (PMID 29142193, 2017). "Unlike in the cases for ovarian cancer, NSCLC and prostate carcinoma, the found PTK6 located in both cytoplasm and nuclei fractions in ESCC." (PMID 23758975, 2013). "In contrast, mice lacking Ptk6 were protected from prostate cancer." (PMID 29142193, 2017). "Targeting PTK6 into the nucleus of prostate cancer cells in vitro negatively regulates growth." (PMID 25153721, 2014). "Introduction of PTEN into a PTEN null prostate cancer cell line leads to dephosphorylation of PY342 but not PY447 and PTK6 inhibition." (PMID 29142193, 2017).
breast tumors (25 papers, 2007 to 2023). "The cytoplasmic tyrosine kinase PTK6 (BRK) shows elevated expression in approximately two-thirds of primary breast tumours, and is implicated in EGF receptor-dependent signalling and epithelial tumorigenesis." (PMID 18781181, 2008). "Various levels of PTK6 protein expression were detected by Western blot in breast tumor cell lines with rank order of T47D = BT474 > MDA-MB-231 = MDA-MB-453 > BT549." (PMID 29879184, 2018). "For example, overexpression of the PTK6 kinase-dead mutant in breast tumor T47D cells promoted cell proliferation at the same level as the PTK6 wild type (WT) protein." (PMID 29879184, 2018). "Protein tyrosine kinase 6 (PTK6), also termed breast tumor kinase (Brk), was initially identified in a metastatic breast tumor, subsequently cloned from mouse intestinal crypt cells and named Src-related intestinal kinase (Sik)." (PMID 27311570, 2016). "Compared with the frequency of ErbB2 overexpression (25%–30%), the high frequency of PTK6 expression (60%–86%) in breast tumor cells suggests that this protein has great potential as a new therapeutic target, especially in patients with no ErbB2 expression." (PMID 27311570, 2016). "PTK6 expression was observed on the plasma membrane in human breast tumors and in cell nuclei in well-differentiated prostate tumors." (PMID 27311570, 2016). "Although most B2;Ptk6−/− mice developed breast tumors after 12 months, tumor initiation was significantly delayed and the survival time was increased." (PMID 26247733, 2015). "Staining of breast tumor tissue microarrays (TMAs) demonstrated increased levels of PTK6 expression that was often in the active form at the plasma membrane in tumor cells." (PMID 25153721, 2014). "The Santa Cruz Biotechnology BRK C-18 polyclonal and BRK G-6 monoclonal antibodies both recognize a specific PTK6 band in breast tumor cell lysates." (PMID 25153721, 2014). "Increased numbers of breast tumor samples will need to be analyzed to determine the statistical significance of the intracellular localization patterns of total and active PTK6 in high versus low grade LCIS and DCIS." (PMID 25153721, 2014). "Our data suggest that it will be important to take the activation status and intracellular localization of PTK6 into account to fully understand its contributions to invasive breast tumors and its potential as a therapeutic target." (PMID 25153721, 2014). "We detected PTK6 mRNA and protein expression in the immortalized normal MCF-10A human mammary gland epithelial cell line, and examined PTK6 expression and activation in a normal human breast tissue microarray, as well as in human breast tumors." (PMID 25153721, 2014). "PTK6 copy number gain (copy number greater than or equal to 3.0) was observed in 15 of 93 breast tumors (15%) in SNP analysis." (PMID 20668531, 2010). "PTK6 maps to a chromosomal region (20q13.3) that is frequently amplified in breast tumors and amplicons spanning this region variably contain other suspected oncogenes, such as TDE1, NCoA3, BCAS4, and ZNF217." (PMID 20668531, 2010). "In previously published microarray analyses of breast tumor specimens downloaded from Oncomine, PTK6 transcript levels were elevated in nearly all breast tumor subtypes with the exception of basal-like tumors." (PMID 20668531, 2010). "PTK6, also known as breast tumor kinase, was originally identified in human breast tumors." (PMID 35401239, 2022). "However, in human breast tumors, striking PTK6 expression and phosphorylation of tyrosine 342 is observed at the plasma membrane." (PMID 25153721, 2014). "BRK/PTK6 drives breast tumor formation in vivo in mouse models and xenografts." (PMID 25594057, 2014). "PTK6 activation may be more significant than total PTK6 expression when evaluating breast tumor pathology." (PMID 25153721, 2014). "Interestingly, in breast tumors expressing high levels of PTK6 P-Y342, luminal A, B and HER2 subtypes contain both IDC and DCIS or LCIS." (PMID 25153721, 2014).
breast tumors (continued). "Furthermore, inhibition of PTK6 expression in breast tumor cells resulted in a moderate decrease in cellular proliferation using small inhibitory RNA." (PMID 23497344, 2013). "We examined PTK6 copy number in a cohort of 93 breast tumors." (PMID 20668531, 2010). "We examined the relative expression of PTK6 mRNA in different breast tumor subtypes." (PMID 20668531, 2010). "This expression pattern may be in part due to copy number gain as PTK6 maps to Chromosome 20q13.3, a region frequently amplified in breast tumors." (PMID 20668531, 2010). "Interestingly, active PTK6 was only detected in human breast tumors, suggesting that PTK6 may have kinase-independent functions in normal human breast tissue that are distinct from its cancer-promoting activities at the membrane." (PMID 26247733, 2015). "Thus, immunohistochemical analyses of breast tumor specimens with attention to PTK6 expression in specific subcellular compartments could be informative." (PMID 20668531, 2010). "Protein tyrosine kinase 6 (PTK6), also known as breast tumor related kinase (BRK), is an intracellular tyrosine kinase highly expressed in human breast tumors." (PMID 25748447, 2015). "A significant correlation between expression of PTK6 and ERBB2 (HER2) has been reported in breast tumors." (PMID 26247733, 2015). "Coamplification and overexpression of PTK6 and ERBB2 was detected in a dataset of 113 Norwegian breast tumors." (PMID 25153721, 2014). "Protein Tyrosine kinase 6 (PTK6/BRK) is overexpressed in the majority of human breast tumors and breast tumor cell lines." (PMID 25153721, 2014). "We also compared methylation profiles for Tamoxifen resistant genes, and identified several hypermethylation genes in breast tumors, such as ACTA1, ISG15, PTK6 and SEPHS2." (PMID 23630576, 2013). "Phosphorylation of the Y342 residue activates PTK6, with active PTK6 being detected in breast tumors but not in normal breast tissues." (PMID 37509364, 2023). "BrdU incorporation into breast tumors was not significantly different and tumor size did not vary significantly between Ptk6+/+ and Ptk6−/− mice, from the time of the initial tumor palpation until the humane end point." (PMID 26247733, 2015). "Although it is well established that PTK6 is expressed in most human breast tumors, the activation status of PTK6 in breast tumors has not been examined." (PMID 25153721, 2014). "The non-receptor PTK termed breast tumor kinase (Brk/PTK6) is overexpressed in approximately 86% of human breast tumors." (PMID 21923922, 2011). "Breast tumor kinase (Brk/protein tyrosine kinase 6 (PTK6)) is a nonreceptor, soluble tyrosine kinase overexpressed in the majority of breast tumors." (PMID 20687930, 2010). "In the early years, Some scholars crossed Ptk6-/- mice with the mouse mammary tumor virus-ERBB2 transgenic mouse line expressing activated ERBB2 and characterized by tumor development and progression, the role of PTK6 in ERBB2-induced breast tumor initiation and metastasis was explored." (PMID 37932734, 2023). "Furthermore, in engineered breast tumor cells overexpressing PTK6, the inhibition of PTK6 kinase activity does not parallel the inhibition of tumor cell growth with a >500-fold shift in compound potencies (IC50 values)." (PMID 29879184, 2018). "Our findings indicate that the induction of PTK6 in ERBB2-induced tumors is physiologically significant, and suggest that targeting PTK6 in ERBB2-positive breast tumors could restrain several signaling pathways that have critical roles in ERBB2-induced tumorigenesis." (PMID 26247733, 2015). "This ability of PTK6 could underpin its critical role in a subset of breast tumors which do not express substantial levels of ErbB receptor family kinases, but rather express high levels of both IGF-1R and PTK6." (PMID 20668531, 2010).
breast tumors (continued). "Treatment of breast tumor cells MDA-MB-231 and MDA-MB-453 with either compound leads to modest cell growth inhibition with similar potency despite their significant differences in PTK6 kinase inhibition, suggesting that their off-target effects may account for the observed tumor growth inhibition." (PMID 29879184, 2018). "Protein tyrosine kinase 6 (PTK6), also known as breast tumor kinase (BRK), is a non-receptor intracellular tyrosine kinase primitively cloned from a metastatic breast tumor patient." (PMID 34551797, 2021). "The phosphorylation of these substrate candidates induced by EGF stimulation (a known PTK6 stimulus) remained unchanged following treatment with PTK6 inhibitors in breast tumor cells MDA-MB-231 and HCC1954 (data not shown), casting a doubt if they are physiological PTK6 substrates in tumor cells." (PMID 29879184, 2018).
colon carcinoma (10 papers, 2011 to 2024). "Aberrant expression of PTK6 is frequently detected in epithelial cancers including breast, ovarian, prostate and colon cancers and linked to tumor formation." (PMID 29879184, 2018). "Of note, PTK6 also exhibits a contrasting role in colon cancer cells versus other tumor types; PTK6 knockdown in SW480 and HCT116 cells promotes EMT and increased growth of SW480 tumor xenografts." (PMID 38457262, 2024). "Co-expression and altered localization of ALT-PTK6 and full-length PTK6 have been detected in human colon cancer cell lines." (PMID 37509364, 2023). "Following activation of PTK6 by DNA damage, PTK6 stimulated STAT3 in the HCT116 colon cancer cell line." (PMID 37509364, 2023). "Additional research is required to clarify the precise functions of PTK6 in normal intestine and colon tumors, including levels of expression, cellular localization, and response to cellular and DNA damaging stresses." (PMID 37509364, 2023). "In colon cancer, PTK6 interacts with JAK2 and increases STAT3 phosphorylation to enhance stemness and chemoresistance." (PMID 35562900, 2022). "It has been reported that PTK6 expression is highest in normal colon epithelial tissues and decreases during colon tumor progression." (PMID 34781983, 2021). "Consistent with our results, miR-214 mimic inhibits proliferation, migration, and invasion of colon cancer, while downregulation promotes colon cancer growth and metastasis via regulation of PTK6." (PMID 34884984, 2021). "Important roles of PTK6 in various cancers, including breast, prostate, and colon cancers have been reviewed." (PMID 34781983, 2021). "Both kinase-dependent and kinase-independent roles for PTK6 have been described in breast and colon tumors." (PMID 29879184, 2018). "For example, PTK6 is overexpressed in invasive ductal breast carcinoma, serous ovarian carcinoma, non-small cell lung cancer, colon carcinoma and head and neck cancers." (PMID 26709519, 2015). "We recently demonstrated that β-catenin is a direct substrate of PTK6, and that PTK6 regulates β-catenin transcriptional activity in the human SW620 colon cancer cell line, and in the mouse intestine." (PMID 21479203, 2011). "Elevated PTK6 expression has been detected in multiple cancers such as breast, prostate, cervical, non-small cell lung, high-grade ovarian, bladder, pancreatic, and colon cancer, where it can promote malignant transformation and progression." (PMID 37509364, 2023). "PTK6 may also play a role in driving differentiation in cancer cells since increased PTK6 expression is also evident in differentiating Caco-2 colon cancer cells." (PMID 37509364, 2023). "Nevertheless, there is still some uncertainty surrounding the role of PTK6 in colon cancer." (PMID 37509364, 2023). "Increased expression and amplification of PTK6 have been reported in multiple tumor types, including breast, prostate, ovarian, skin, lung, and colon cancer, and a growing body of evidence indicates that PTK6 plays important roles in promoting tumorigenesis (reviewed in." (PMID 36228719, 2022). "In addition, the disruption of PTK6 in mice impaired STAT3 activation and protected animals from AOM/DSS-induced colon cancer, indicating that this substrate could be a key mediator for PTK6’s role in DNA damage-induced CRC." (PMID 37509364, 2023). "In addition, it is reported that the PTK6 gene is amplified in colon cancer." (PMID 37509364, 2023). "Similarly, when DNA-damaging agents such as radiation and chemotherapy drugs (e.g., 5-fluorouracil) were used in colon cancer cells, PTK6 expression promoted survival of these cells, again suggesting an important role for PTK6 following treatment with DNA damaging agents." (PMID 37509364, 2023). "PTK6 promotes STAT3 and ERK5 activation to promote cell survival and response to DNA-damaging treatments in colon cancer cells." (PMID 35562900, 2022).
colon carcinoma (continued). "Repression of the β-catenin/TCF transcriptional targets Cyclin D1 and c-Myc were observed in cells transfected with PTK6 YF (- ALT-PTK6), similar to what we previously observed in the SW620 colon cancer cell line." (PMID 21479203, 2011). "Analysis of PTK6 transcripts expressed in BPH1, DU145 and PC3 prostate cell lines, and HCT116, LIM1215 and SW480 colon cancer cell lines showed the presence of full-length and alternatively spliced transcripts." (PMID 21479203, 2011). "PTK6 knockdown resulted in a decrease in E-cadherin and ZO-1 epithelial markers and an increase in vimentin, ZEB1, and claudin-1 mesenchymal markers via STAT3-MEK5/ERK5 in colon cancer cells, which was reversed by PTK6 reintroduction." (PMID 33572742, 2021). "Similarly, PTK6 was able to promote epithelial characteristics in colon cancer cell lines independent of kinase activity." (PMID 37509364, 2023).
ovarian carcinoma (10 papers, 2006 to 2023). A malignant neoplasm originating from the surface ovarian epithelium. "The expression of PTK6 was also associated with the poor prognosis of patients with non-small cell lung cancer and ovarian cancer." (PMID 34551797, 2021). "The also found that PTK6 primarily located at the cytoplasm of ovarian cancer cells, however, in a subset of tumor cells, staining was observed in the nuclei." (PMID 23758975, 2013). "In our study, PTK6 was found to be located primarily in cytoplasmic compared to in the nuclei fractions in NPC, this result was similar with the previous study of the expression of PTK6 in ovarian carcinoma, NSCLC and poorly differentiated prostate cacinoma." (PMID 23758975, 2013). "PTK6 is an attractive potential therapeutic target for breast and ovarian cancer for several reasons." (PMID 20668531, 2010). "PTK6 has been reported to be expressed in multiple tumor types, including breast and ovarian cancer." (PMID 20668531, 2010). "Downregulation of PTK6 also prevented IGF-1 stimulated anoikis resistance of DOV-13 ovarian cancer cells, which co-express PTK6 and IGF-1R." (PMID 20668531, 2010). "PTK6 downregulation induces apoptosis of breast and ovarian cancer cells deprived of matrix attachment, whereas its overexpression enhances survival." (PMID 20668531, 2010). "Also, PTK6 gene was amplified at low levels in primary ovarian cancer and its protein level was highly expressed in the majority of high-grade serous carcinomas and ovarian cancer cell lines but not the normal ovary." (PMID 23758975, 2013). "Furthermore, similar changes in IGF-1 receptor phosphorylation were observed with downregulation of PTK6 in attached DOV-13 ovarian cancer cells." (PMID 20668531, 2010). "We sought to determine whether PTK6 plays a critical role in modulating anchorage-independent survival of breast and ovarian cancer cells in which PTK6 is highly expressed, particularly those which co-express IGF-1R." (PMID 20668531, 2010). "PTK6 was also found to be required for anchorage independence of breast and ovarian cancer cells." (PMID 20668531, 2010). "Several putative oncogenes were differentially expressed in MOC, including the breast tumour kinase BRK (PTK6) not previously implicated in ovarian cancer pathogenesis; and MST1R/RON, a receptor tyrosine kinase associated with proliferation and motility of cancer cells including ovarian carcinoma." (PMID 16508639, 2006). "Furthermore, PTK6 has previously been reported to be amplified and overexpressed in a significant number of ovarian cancers although its functions in ovarian tumorigenesis have not been studied." (PMID 20668531, 2010).